HORMAD2 (HORMA domain containing 2)
Description:
Essential for synapsis surveillance during meiotic prophase via the recruitment of ATR activity. Plays a key role in the male mid-pachytene checkpoint and the female meiotic prophase checkpoint: required for efficient build-up of ATR activity on unsynapsed chromosome regions, a process believed to form the basis of meiotic silencing of unsynapsed chromatin (MSUC) and meiotic prophase quality control in both sexes. Required for the DNA double-strand break-independent, BRCA1-dependent activation of ATR on the sex chromosomes that is essential for normal sex body formation (By similarity).
Synonyms: MGC26710; CT46.2
Tractability: No criterion of Open Targets' tractability assessment is met for any kind of drug.
Gene: Protein-coding gene on chromosome 22 (30,080,464 to 30,177,075, forward strand). Ensembl gene ENSG00000176635.
Subcellular location: Nucleus; Chromosome
Subcellular location (Human Protein Atlas): Nucleoplasm; Centrosome; Cytosol
Gene Ontology:
Molecular function: protein binding
Biological process: meiotic cell cycle; meiotic recombination checkpoint signaling; meiotic sister chromatid cohesion; synaptonemal complex assembly
Cellular component: nucleoplasm; chromosome; nucleus; synaptonemal complex
Genetic constraint (gnomAD): Loss-of-function variants: 15 observed, 15.1 expected, observed/expected ratio (o/e) 0.99, 90% interval 0.66 to 1.52. The upper end of that interval is the gene's LOEUF score, 1.52, which puts it in group 6 of 6, group 1 being the genes least tolerant of losing a copy. Missense variants: 200 observed, 227.43 expected, observed/expected ratio (o/e) 0.88, 90% interval 0.78 to 0.99. Synonymous variants: 83 observed, 82.71 expected, observed/expected ratio (o/e) 1, 90% interval 0.84 to 1.21.
Homologues: Orthologues: chimpanzee HORMAD2 (99% identical), macaque HORMAD2 (93% identical), dog HORMAD2 (87% identical), pig HORMAD2 (83% identical), guinea pig HORMAD2 (78% identical), mouse Hormad2 (77% identical), rabbit HORMAD2 (76% identical), rat Hormad2 (75% identical), Caenorhabditis elegans him-3 (20% identical), Caenorhabditis elegans htp-2 (16% identical), Caenorhabditis elegans htp-1 (15% identical). Paralogues in human: HORMAD1 (50% identical).
Diseases named in the same sentence as HORMAD2 in open-access papers:
HORMAD2 is named in the same sentence as 30 diseases in open-access papers, as found by Europe PMC text mining. Sharing a sentence is not in itself a finding about the gene and the disease. The quoted sentences say what the papers report.
IgA nephropathy (6 papers, 2014 to 2024). "ITGAM–ITGAX (rs11150612, rs11574637), VAV3 rs17019602, CARD9 rs4077515, DEFA (rs2738048, rs10086568), and HORMAD2 rs2412971 are mucosal immune defence polymorphisms, that have an impact on IgA production, described as risk loci for IgA nephropathy (IgAN)." (PMID 37685869, 2023). "Genome-wide Association Study (GWAS) found that susceptibility genes of CARD9 and HORMAD2 for IgA nephropathy were also associated with IBD." (PMID 35850695, 2022). "Several loci associated with IgA nephropathy, such as CARD9 and HORMAD2, have also been associated with the risk of IBD." (PMID 39421866, 2024). "rs713875 is a C/G variant located downstream of the HORMAD2 and LIF genes that has been implicated in multiple diseases, including Crohn's disease, IgA nephropathy and early-onset inflammatory bowel disease." (PMID 24911414, 2014). "A single deletion in both CFHR1 and CFHR3 confers a 30% reduction in the risk of IgA nephropathy, and a meta-analysis with risk-score model including Asian, European, and African population evaluated five susceptibility loci of three MHC, one CHF and one HORMAD2." (PMID 34354705, 2021).
inflammatory bowel disease (4 papers, 2012 to 2023). A spectrum of small and large bowel inflammatory diseases of unknown etiology. "Interestingly, many of the IgAN loci are known to exhibit opposing effects on other autoimmune conditions; for example, the HLA-DQB1 and HORMAD2 risk alleles are respectively protective for systemic lupus erythematosus, and inflammatory bowel disease." (PMID 22737082, 2012).
Crohn disease (3 papers, 2014 to 2023). A gastrointestinal disorder characterized by chronic inflammation involving all layers of the intestinal wall, noncaseating granulomas affecting the intestinal wall and regional lymph nodes, and transmural fibrosis. "Finally, HORMAD2 is described as a protective locus against Crohn’s disease and is associated with increased serum IgA levels." (PMID 37685869, 2023).
thyroid cancer (3 papers, 2018 to 2025). "This outcome implied that demethylation of HORMAD2 can induce more apoptotic thyroid cancer cells as well as inhibit thyroid cancer cells mitosis." (PMID 30039914, 2018). "The expression of HORMAD2 was high in normal thyroid follicular epithelial cell lines of Nthy‐ori 3‐1 cells but decreased markedly in thyroid cancer cells of FTC‐133, SW579 and TPC‐1 cells, especially in TPC‐1cells (P < .01)." (PMID 30039914, 2018). "The differentially methylated region DMR_19 enriched with HORMAD2 was significantly hypermethylated in thyroid cancer tissues and the heatmap displayed top 20 different methylation genes enriched in THCA tissues, in which HORMAD2 was hypermethylated." (PMID 30039914, 2018). "The expression of HORMAD2 was detected by qRT‐PCR and Western blot in human thyroid cancer cells and normal thyroid follicular epithelial cells." (PMID 30039914, 2018). "HORMAD2 dysregulation through either SNPs or hypermethylation is attributed to poor survival in non-small cell lung cancer (NSCLC) and thyroid carcinoma." (PMID 34090518, 2021). "After treatment with 5‐Aza, HORMAD2 expression was up‐regulated in THCA cells and its overexpression can suppress thyroid cancer cell viability, mobility and invasiveness remarkably." (PMID 30039914, 2018). "Up‐regulation of HORMAD2 in THCA cells could prolong G0/G1 phase and shorten S phase to impede cell mitosis as well as promote thyroid cancer cells apoptosis." (PMID 30039914, 2018).
lung adenocarcinoma (2 papers, 2017 to 2022). A carcinoma that arises from the lung and is characterized by the presence of malignant glandular epithelial cells. "And also HORMAD2 has been identified as a CT (cancer-testis) gene by silico methods which indicate that HORMAD2 may contribute to the lung adenocarcinoma risk." (PMID 28903315, 2017).
lung carcinoma (2 papers, 2017 to 2022). "Among the downregulated and hypermethylated genes associated with both RMST and DIRC3 (including BNIPL, HORMAD2, and NPHP3), HORMAD2 is the only gene related to lung cancer." (PMID 35356464, 2022). "Of special interest is that most of these RNAs had not been reported in lung cancers and two genes (HORMAD2 and TRIM7) might associate with virus infection." (PMID 35356464, 2022).
systemic lupus erythematosus (2 papers, 2012 to 2024). An autoimmune multi-organ disease typically associated with vasculopathy and autoantibody production. "Some of the loci involved in IgAN, such as CARD9 or HORMAD2, are shared with IBD, and have also been associated with immune-mediated diseases, such as Systemic Lupus Erythematosus (SLE)." (PMID 39768250, 2024).
asthma (1 paper, 2024). "Single gene GSEA analysis revealed that HORMAD2, WNT10A, ATP6V1E2, CMBL, ARRDC4, and LPIN2 were primarily involved in Allograft rejection, Arginine biosynthesis, Asthma, and Fatty acid biosynthesis." (PMID 40635857, 2024).
fibrosis (1 paper, 2017). the formation of excess fibrous connective tissue in an organ or tissue in a reparative or reactive process. "In our meta-analysis, expression of HORMAD2 decreased with advancing fibrosis in NAFLD." (PMID 28955037, 2017).
Infertility (1 paper, 2018). "The biological processes significantly represented among differentially expressed genes included mitochondrial function (Mrps31 and Trit1), cell senescence (Gpx6, Lamtor1 and Hist1h1e), cell growth (Hormad1 and Hormad2), infertility (Sycp3), and embryo development (Gli3)." (PMID 29851234, 2018).
oral diseases (1 paper, 2023). "In the oral diseases, we observed one MTS locus for DPPT implicating HORMAD2 with a credible set overlapping that of CDTA at the same locus." (PMID 36653354, 2023).
virus infection (1 paper, 2022). "The deregulation and methylation levels of HORMAD2 and TRIM7 in recurrent LUSC tissues might provide references for exploring the potential association of LUSC prognosis with virus infection." (PMID 35356464, 2022).
cancer (6 papers, 2016 to 2025). A tumor composed of atypical neoplastic, often pleomorphic cells that invade other tissues. "The homologous protein HORMA Domain Containing 2 (HORMAD2) also has cancer-testis-associated expression profile." (PMID 27275820, 2016). "MiR-12194-3p was associated with decreased HORMAD2, a signal responsive adapter mediating protein–protein interactions, and reduced LRCC4B, which results in cell proliferation in cancer cell lines." (PMID 40725010, 2025). "Even though the homologous protein HORMAD2 was found to be aberrantly expressed in lung cancer tissues, its potential role in modulating DNA repair in cancer cells is less clear." (PMID 35251135, 2022). "However, follow-up studies are needed to investigate a direct involvement of HORMAD2 in promoting cancer cell’ growth." (PMID 35251135, 2022). "Therefore, putative effects of HORMAD1 on genome stability in cancer are likely to result from neomorphic activities unrelated to its HORMAD2 and CCDC36-mediated roles in germ cell development." (PMID 30333500, 2018). "However, HORMAD2 is not expressed in H1299 cells and therefore the IRIF activity of HORMAD1 in cancer cells is HORMAD2-independent." (PMID 30333500, 2018). "Herein, we mainly studied on methylation status of HORMAD2 promoter, and verified for the first time that HORMAD2 was aberrantly methylated in THCA in tissues and cells, which might lead to cancer progression and tumorigenesis." (PMID 30039914, 2018). "The HORMAD2- and CCDC36-independence of DSB repair in our HR assays is consistent with the hypothesis that HORMAD1 acquires neomorphic DNA repair activities when mis-expressed in cancer cells." (PMID 30333500, 2018).
tumour (1 paper, 2018). "Furthermore, tumour formation assay showed that increased HORMAD2 level impeded tumour growth in vivo." (PMID 30039914, 2018). "The result illustrated HORMAD2 can suppress tumour growth to a large degree." (PMID 30039914, 2018).
HORMAD2 also shares sentences with these, for which no sentence is quoted: hypothyroidism (2 papers); apical periodontitis (1); cancer-testis (1); deep vein thrombosis (1); gastroduodenal ulcer (1); intestinal disease (1); leukemia (1); myeloma (1); nephronophthisis (1); non-small cell lung carcinoma (1); pulpitis (1); thyroid (1); thyroid tumour (1); type 1 diabetes (1); type 2 diabetes (1); ulcerative colitis (1).